TMEM60 (transmembrane protein 60)
Synonyms: C7orf35; DC32
Tractability: Antibody: UniProt predicts a signal peptide or a membrane-spanning region.
Gene: Protein-coding gene on chromosome 7 (77,793,728 to 77,799,484, reverse strand). Ensembl gene ENSG00000135211.
Subcellular location: Membrane
Gene Ontology:
Molecular function: protein binding
Cellular component: membrane
Genetic constraint (gnomAD): Loss-of-function variants: 4 observed, 11.24 expected, observed/expected ratio (o/e) 0.36, 90% interval 0.17 to 0.81. The upper end of that interval is the gene's LOEUF score, 0.81, which puts it in group 3 of 6, group 1 being the genes least tolerant of losing a copy. Missense variants: 127 observed, 160.36 expected, observed/expected ratio (o/e) 0.79, 90% interval 0.69 to 0.92. Synonymous variants: 56 observed, 60.45 expected, observed/expected ratio (o/e) 0.93, 90% interval 0.75 to 1.16.
Homologues: Orthologues: chimpanzee TMEM60 (100% identical), mouse Tmem60 (99% identical), rabbit TMEM60 (99% identical), dog TMEM60 (98% identical), guinea pig TMEM60 (98% identical), macaque TMEM60 (98% identical), pig TMEM60 (98% identical), rat Tmem60 (98% identical), tropical clawed frog tmem60 (83% identical), Drosophila melanogaster CG13919 (29% identical). Paralogues in human: TMEM185B (28% identical), TMEM185A (25% identical).
Diseases named in the same sentence as TMEM60 in open-access papers:
TMEM60 is named in the same sentence as 7 diseases in open-access papers, as found by Europe PMC text mining. Sharing a sentence is not in itself a finding about the gene and the disease. The quoted sentences say what the papers report.
glioma (4 papers, 2022 to 2023). A benign or malignant brain and spinal cord tumor that arises from glial cells (astrocytes, oligodendrocytes, ependymal cells). "To draw a conclusion, we analyzed the expression of TMEM60 in 30 clinical samples and found that it is highly expressed in gliomas, and thus, it has a prognostic and diagnostic value." (PMID 36744183, 2022). "Association of TMEM60 expression is with the clinicopathological characteristics of patients with glioma." (PMID 36744183, 2022). "In the present study, univariate analysis results (HR = 3.97, 95% CI = 3.211–4.909, p < .001) showed that TMEM60 is a risk factor for glioma patients in TCGA, whereas multivariate analysis results (HR = 1.32, 95% CI = .935–1.868) were not statistically significant." (PMID 36744183, 2022). "Overall, information from databases and clinical samples revealed that TMEM60 is a risk factor and could be used as a prognostic biomarker for glioma patients." (PMID 36744183, 2022). "In LN229 cell line, we also proved that silencing TMEM60 can inhibit the proliferation of glioma cells." (PMID 36744183, 2022). "We found transmembrane protein 60 was significantly upregulated in glioma compared with that in normal brain tissue at the mRNA." (PMID 36744183, 2022). "The function of TMEM60 has also been studied in tumors, and elevated levels of TMEM60 lead to enhanced glioma proliferation, migration, and invasion, inhibit apoptosis and promote PI3K/Akt activation." (PMID 36698419, 2022). "TMEM60 expression levels in the IDH wild-type glioma subgroup gradually increased with the higher WHO grade in TCGA (p < .001) and CGGA (p < .001)." (PMID 36744183, 2022). "Our analysis showed that the expression of TMEM60 in the IDH wild-type glioma subtype was higher than that in the IDH mutant subtype of TCGA (p < .001) and CGGA (p < .001)." (PMID 36744183, 2022). "A similarly conducted study also found that TMEM60 promotes glioma cell proliferation, migration, and invasion and impairs cell apoptosis via activating the PI3K/Akt signaling pathway." (PMID 36425564, 2022). "Our study showed that TMEM60 is abnormally highly expressed in gliomas using data from multiple centers, populations, and clinical samples." (PMID 36744183, 2022). "This is the 0 report on the abnormally high expression of transmembrane protein 60 in glioma and its related clinical features, such as tumor microenvironment, immune response, tumor heterogeneity, and patient prognosis." (PMID 36744183, 2022). "We also found that transmembrane protein 60 silencing weakened the proliferation and colony formation of glioma LN229 cells." (PMID 36744183, 2022). "We previously verified that TMEM60 is abnormally highly expressed in glioma and is related to the prognosis of glioma patients; thus, it can be used clinically as an independent prognostic and diagnostic factor." (PMID 36744183, 2022). "We used bioinformatic methods and basic experiments to verify the expression of transmembrane protein 60 in gliomas and its relationship with 1p and 19q (1p19q) status, isocitrate dehydrogenase (IDH) status, patient prognosis, and immune cell infiltration using public databases and clinical samples." (PMID 36744183, 2022). "Thus, we inhibited the expression of transmembrane protein 60 to observe the proliferation and activity of glioma LN229 cells." (PMID 36744183, 2022). "IDH status, as a biomarker for the prognosis of glioma, has been clinically applied, but its relationship with TMEM60 remains unclear." (PMID 36744183, 2022). "In addition, TMEM60 expression was significantly upregulated in high-grade IDH mutant glioma patients of TCGA (p < .001) and CGGA (p < .001)." (PMID 36744183, 2022). "We also found that the World Health Organization (WHO) grade was positively correlated with the expression of TMEM60 in glioma using data from TCGA RNA-seq (p < .001), CGGA RNA-seq (p < .001), CGGA mRNA-array (p < .001), and 30 clinical glioma samples (p < .05)." (PMID 36744183, 2022).
glioma (continued). "This is the first report on the abnormally high expression of TMEM60 in various glioma cell lines." (PMID 36744183, 2022). "In addition, TMEM60 was significantly upregulated in glioma compared with normal brain tissue from TCGA (p < .001), GSE116520 (p < .001), and GSE153692 (p < .05), However, there are no meaningful results in the CGGA database." (PMID 36744183, 2022). "Finally, we found that transmembrane protein 60 silencing weakened the viability, proliferation, and colony formation of glioma LN229 cells." (PMID 36744183, 2022). "Therefore, information from databases, clinical samples, and basic experiments revealed that TMEM60 is a new oncogene closely related to glioma patients’ prognosis with high potential for use as a therapeutic target." (PMID 36744183, 2022). "Therefore, TMEM60 might be a molecular marker that could be used as a new therapeutic target for glioma treatment." (PMID 36744183, 2022). "Thus, the new oncogene transmembrane protein 60 might be an effective therapeutic target for the clinical treatment of glioma." (PMID 36744183, 2022). "In this study, we showed that TMEM60 combined with 1p19q and IDH has guiding significance for treating glioma." (PMID 36744183, 2022). "Based on the TIMRE database, the expression of TMEM60 was positively correlated with the number of cells infiltrated by CD8+ T-cells and macrophages in low-grade glioma." (PMID 36744183, 2022). "Thus, it is necessary to explore the molecular and clinical characteristics of newly identified oncogenes, such as transmembrane protein 60 (TMEM60), to develop effective treating options for glioma." (PMID 36744183, 2022). "In the subgroups of World Health Organization high grade, isocitrate dehydrogenase wildtype, 1p and 19q non-codeletion, or isocitrate dehydrogenase wild combined with 1p and 19q non-codeletion, the expression of transmembrane protein 60 increased, and the prognosis of glioma patients worsened." (PMID 36744183, 2022).
fragile X syndrome (1 paper, 2016). A genetic syndrome caused by mutations in the FMR1 gene which is responsible for the expression of the fragile X mental retardation 1 protein. "This domain has been identified to be involved with the Fragile-X syndrome through the protein TMEM185A, however TMEM203 and TMEM60 share only ~10 % identity to the TMEM185A/B proteins and ~21 % identity between each other." (PMID 27030248, 2016).
renal dysfunction (1 paper, 2021). "This study has replicated APOL1 gene variants: (G1)-rs73885319 and (G2)-rs71785313, shown to be strongly associated with renal dysfunction in SCD patients, as well as A1CF-rs10994860, SYPL2-rs12136063, WNT7A-rs6795744, and TMEM60-rs6465825 in Cameroonian SCD patients." (PMID 33790942, 2021).
cancer (2 papers, 2022 to 2023). A tumor composed of atypical neoplastic, often pleomorphic cells that invade other tissues. "Similarly, we are unaware of previous reports linking TMEM60 to GBM or other cancers." (PMID 35875673, 2022).
tumor (2 papers, 2022 to 2023). "The SCNA module provided a comparison of tumor infiltration levels among tumors with different somatic copy number alterations for TMEM60 deep deletion (−2), arm-level deletion (−1), diploid/normal, arm-level gain, and high amplification." (PMID 36744183, 2022). "In the transmembrane protein 60 high expression group, infiltration of immune cells and stromal cells in the tumor microenvironment increased, tumor purity decreased, and immune cells and pathways were activated." (PMID 36744183, 2022). "Consequently, the abnormally high expression of TMEM60 affects the distribution of macrophages, Tregs, and other immune cells, increases tumor heterogeneity, and promotes tumor resistance to treatment, resulting in poor patient prognosis." (PMID 36744183, 2022). "However, it is still unclear how TMEM60 regulates immune resistance to promote tumor malignant progress, although we analyze that it may be related to neutral mediated immunity." (PMID 36744183, 2022). "In addition, TMEM60 might participate in the process of tumor formation through the cell cycle and inhibit anti-tumor immunity by promoting the infiltration of Tregs and macrophages M0." (PMID 36744183, 2022). "We found that the clinical characteristics of patients with high TMEM60 expression levels were mainly IDH wild-type, 1p19q non-codel, WHO grade IV, >42 years of age, increased immune cells and stromal cells, decreased tumor purity, and increased activation of immune cells or pathways." (PMID 36744183, 2022). "The clinical characteristics of patients in the high TMEM60 expression group were mainly 1p19q non-codel, IDH wild-type, >42 years of age, WHO III–WHO IV grade, increased immune cells and stromal cells, decreased tumor purity, and increased activation of immune cells and pathways." (PMID 36744183, 2022).
TMEM60 also shares sentences with these, for which no sentence is quoted: gastric cancer (1 paper); lymphoma (1).